RNASE12 (ribonuclease A family member 12 (inactive))
Description:
Does not exhibit any ribonuclease activity.
Synonyms: RAI1; HEL-S-85p
Tractability: Antibody: UniProt places it where antibodies can reach, with high confidence; UniProt predicts a signal peptide or a membrane-spanning region; its Gene Ontology location is reachable by antibodies, with medium confidence.
Gene: Protein-coding gene on chromosome 14 (20,590,073 to 20,591,376, reverse strand). Ensembl gene ENSG00000258436.
Subcellular location: Secreted
Gene Ontology:
Molecular function: RNA nuclease activity; nucleic acid binding
Biological process: defense response to Gram-positive bacterium
Cellular component: extracellular region
Genetic constraint (gnomAD): Loss-of-function variants: 0 observed, 0.72 expected, observed/expected ratio (o/e) 0, 90% interval 0 to 1.79. That is too few expected variants to judge how well the gene tolerates losing a copy. Missense variants: 161 observed, 187.54 expected, observed/expected ratio (o/e) 0.86, 90% interval 0.75 to 0.98. Synonymous variants: 55 observed, 63.06 expected, observed/expected ratio (o/e) 0.87, 90% interval 0.7 to 1.09.
Homologues: Orthologues: chimpanzee RNASE12 (99% identical), pig RNASE12 (72% identical), dog RNASE12 (71% identical), rat Rnase12 (70% identical), mouse Rnase12 (67% identical), guinea pig RNASE12 (63% identical). Paralogues in human: RNASE10 (26% identical), RNASE11 (23% identical), RNASE4 (23% identical), RNASE9 (22% identical), RNASE1 (21% identical), RNASE8 (20% identical), RNASE6 (20% identical), RNASE7 (20% identical), ANG (19% identical), RNASE13 (19% identical), RNASE2 (14% identical), RNASE3 (13% identical).